EP300 (EP300 lysine acetyltransferase)
Diseases named in the same sentence as EP300 in open-access papers (continued):
Sharing a sentence is not in itself a finding about the gene and the disease.
tumor (continued). "This implies that a broad-based search for tumor types with exceptional responses to domain-specific EP300/CBP-targeted therapeutics would be a high-yield approach to identifying tumors for specific inhibition." (PMID 38664416, 2024). "We used these tools to investigate the relative contribution of the EP300/CBP BRD or HAT domain to tumor cell growth." (PMID 38664416, 2024). "In this study, we investigated the dependence of EP300/CREBBP in MLL-r AML and evaluated the anti-tumor efficacy of EP300/CREBBP inhibitor." (PMID 38693103, 2024). "The results indicated that EP300 deletion has a considerable negative effect on tumor proliferation, stemness, migration, and invasion, thus indicating that EP300-enhanced glycolysis is essential for the maintenance of tumor malignant phenotype." (PMID 38256128, 2024). "BMP4 was slightly upregulated in stage IVA patients, while the EP300 gene was remarkably upregulated as the tumor stage advanced, especially in stage III patients." (PMID 38539520, 2024). "Our study elucidates that HK3-mediated O-GlcNAcylation of EP300 is involved in tumor immune evasion." (PMID 39179546, 2024). "As expected, the results of tumor formation experiments suggested that EP300 knockout surely suppressed the tumor growth of LUAD." (PMID 38256128, 2024). "In the context of previous research, our findings align with studies highlighting the role of PIK3CA and EP300 in tumor progression and VM formation." (PMID 39165361, 2024). "In our own cohort, we noted lower EP300 expression compared to adjacent normal tissues through qRT-PCR analysis, but higher expression at the protein level in tumor tissues, as confirmed by WB analysis." (PMID 39179546, 2024). "To obtain in vivo proof, we injected WT and EP300-KO cells subcutaneously in nude mice to create tumor-bearing mice models." (PMID 38256128, 2024). "Instead, the tumor showed CREBBP::BCORL1 fusion and pathogenic mutations in BCOR and CREBBP, along with a DNA methylation profile matching the “CNS tumor with EP300:BCOR(L1) fusion” methylation class." (PMID 38216991, 2024). "CREBBP/EP300 also function as tumor suppressors, but the number of agonists and relevant preclinical studies is relatively rare, which requires further research." (PMID 36831561, 2023). "Colony formation assays further demonstrated that the knockdown of EP300 decreased RSL3-induced tumor growth suppression." (PMID 37696842, 2023). "CREBBP/EP300 participate in tumor immune regulation by modulating the function of immune cells through various pathways." (PMID 36831561, 2023). "Taken together, these results suggest that CREBBP/EP300 are involved in tumor immune responses by regulating immune cell functions, including Tregs differentiation, macrophage M2 polarization, and immune surveillance and killing functions of NK cells." (PMID 36831561, 2023). "CREBBP/EP300 also participate in tumor immune responses by regulating the differentiation and function of multiple immune cells." (PMID 36831561, 2023). "Kaplan–Meier tumor-free survival analysis further revealed that the overexpression of EP300 reduced PDAC the survival rate of patient." (PMID 37696842, 2023). "The higher dose (15 mg/kg ETC-159/d) treatment led to tumor shrinkage in both groups, but in the EP300-knockout group, all tumors regrew after 2 to 3 weeks." (PMID 35536676, 2022).
tumor (continued). "While low-dose ETC-159 treatment (5 mg/kg/d) showed a statistically significant approximately 75% inhibition of control tumor growth, it had a minimal and insignificant effect on the growth of EP300-knockout tumors." (PMID 35536676, 2022). "In contrast, the number of lumina in EP300-knockout tumors was clearly reduced and these tumor cells tended to form solid multilayers with vague epithelial features." (PMID 35536676, 2022). "Consistent with the results of the 24-gene validation experiment, EP300-KO CD4+ T cells killed target tumor cells significantly more quickly than did WT cells." (PMID 35990699, 2022). "Meanwhile the KLF12-transcribed LncRNA-PACERR interacts directly with KLF12 and the KLF12/PACERR complex activates LncRNA-PACERR transcription by recruiting EP300, thereby promoting M2 polarization and pro-tumour function in TAMs." (PMID 35526050, 2022). "APOA1 and APOA2 were observed to be associated with E1A binding protein p300 (EP300) and CREB binding protein (CREBBP) which play an important role in tumor metastasis." (PMID 36428687, 2022). "In this study, we demonstrated that inhibition of ALKBH5 suppresses tumor growth in vivo and that EP300-induced H3K27ac activation promotes ALKBH5 expression." (PMID 33428593, 2021). "KAT2A, SP140 and BRD9 protein expression was higher in tumor tissues, and SMARCA2, BRPF3, KAT2B and EP300 protein expression was lower in the tumor tissues." (PMID 34149798, 2021). "Consistently, genetic EP300 ablation attenuates AR expression and inhibits tumor formation in a mouse model of PTEN deletion-induced tumorigenesis in vivo." (PMID 34201346, 2021). "In B-lymphoma murine models, xenografted tumors bearing CREBBP/EP300 mutation presented lower H3K27 acetylation, higher M2 macrophage recruitment, and more rapid tumor growth than those with CREBBP/EP300 wild-type control via FBXW7-NOTCH-CCL2/CSF1 axis." (PMID 33431788, 2021). "Later, overexpression plasmids of SMYD2 and EP300 successfully abrogated the anti-tumor effects of sh-LINC01605 in vitro, which corroborated our theory again." (PMID 34544413, 2021). "Somatic mutations in CREBBP and EP300 are reported in different benign and malignant tumors, and an association between RSTS patients and tumor development has been investigated." (PMID 33807238, 2021). "Knockdown of EP300 eliminated CSCs in vitro and decreased tumor initiating as well as metastatic potential in vivo." (PMID 33167919, 2020). "We report a novel oncogenic role for EP300 in driving CSC phenotype representing a potential target to address tumor initiation and metastatic spread in TNBC and basal-like BC." (PMID 33167919, 2020). "The results showed the EP300 KD abolishes metastatic colonization and spread in the form of circulating tumor cells in TNBC cells." (PMID 33167919, 2020). "Among the nuclear factors, EP300 is a transcriptional co-activator of which the K1550 site showed increased acetylation level in tumor tissues." (PMID 33093847, 2020). "Next, we analyzed the expression level of EP300 by immunohistochemical analysis based on tissue microarray including 65 of ESCC tumor tissues and paired normal tissues." (PMID 31632486, 2019). "In contrast to our results, Gao' study showed that depletion of EP300 significantly increased tumor cell proliferation in two ESCC cell lines and ectopic expression of wild- type EP300 reversed this effect." (PMID 31632486, 2019). "Here, our results in vitro in ESCC cell lines shows that EP300 function as an oncogene exerting tumor promotion effects, which has been demonstrated in lung, colon, prostate and breast cancers." (PMID 31632486, 2019). "We identified 2 novel in-frame fusion genes, EP300-BCORL1 (exon 31-exon 4) in one grade III tumor (EP3) and FOXO1-STK24 (exon 1-exon 3) in one grade II tumor (EP57)." (PMID 30514397, 2018). "Both proteins encoded by EP300 and CREBBP are suggested as tumor suppressors and indicative of poor prognosis in ESCC." (PMID 29506494, 2018).
tumor (continued). "While this evidence implicates CBP/EP300 as tumor suppressors, evidence also supports their oncogenic activity." (PMID 26731516, 2016). "EP300 is a tumor-related transcription factor that is involved in restraining cell growth and division." (PMID 25520040, 2014). "Of the 309 unique, validated mutations identified through sequencing of the TCGA GBM tumor samples, CTNNB1, EP300, STAT3, and TOP1 also appear in the 50-gene subnetwork signature." (PMID 24068912, 2013). "Notably, increased EP300 expression was detected in HBV‐positive HCC tumor tissues and cells compared to control counterparts." (PMID 40095759, 2025). "We found that p300 (EP300 gene) had increased expression in tumor vs. normal HNC dataset." (PMID 40810390, 2025). "While the tumor-specific frequency of CREBBP and EP300 mutations constrains the analysis in small cohorts, these findings further support their role as biomarkers of immunotherapy response and underscore the need for expanded datasets and prospective validation." (PMID 41301688, 2025). "Therefore, inhibition of EP300 has promising potential to inhibit myeloid mimicry in RMC tumor cells." (PMID 41290625, 2025). "Notably, increased mRNA expression and positive staining of EP300 were determined in the tumor tissues." (PMID 40095759, 2025). "Moreover, IGF2BP1 stabilized EP300 mRNA in an m6A‐dependent manner, forming a positive feedback loop comprising EP300–CMTM6–IGF2BP1–EP300 (mRNA), thereby further enhancing tumor stemness and GEM resistance in PDAC." (PMID 39488785, 2024). "Given their morphological and epigenetic similarities, circumscribed CNS tumors with EP300/CREBBP::BCOR(L1) fusions and CNS tumors with BCOR ITD may represent variants of the same tumor type." (PMID 38216991, 2024). "This hypothesis is consistent with our findings that EP300/CBP bromodomain inhibition has enhanced effects on these tumor cells." (PMID 38664416, 2024). "Although it is known that genome ploidy contributes to tumour malignancy and inferior survival, we found that clonal mutations of CREBBP/EP300 associated with acquired genome duplication cause relapse and thereby provide a clear genetic mechanism of drug resistance." (PMID 38480884, 2024). "Interestingly, EP300 also has tumor suppressor effects in several different clinically relevant MDS models driven by mutations in epigenetic regulators TET2, ASXL1, and SRSF2, respectively, inhibiting the malignant transition of MDS to AML." (PMID 36831561, 2023). "Fifteen additional, potential tumour suppressor genes under the control of Notch or modulating Notch downstream functions have been identified in an animal model of HNSCC, including Adam10, Ripk4, EP300, and Ajuba28, which adds emphasis to the tumour suppressor function of Notch signalling." (PMID 37607974, 2023). "In addition, it was proposed that RHOA is required for stiffness-mediated phosphorylation of AKT and EP300 and the concomitant transcription of more than 20 tumor-promoting factors, including CXCL12, IL11, IL6, VEGFA, PDGFA and PDGFB, FGF, and CTGF." (PMID 37569677, 2023).
tumor (continued). "By analyzing the association between RBM14 expression and EP300 and YY1 levels using TIMER database, we found that RBM14 expression was strongly associated with the expression of EP300, CBP, and CTCF in various types of tumor tissues." (PMID 37060064, 2023). "CREBBP/EP300 act as tumor suppressors and maintain normal hematopoietic function." (PMID 36831561, 2023). "This suggests that the role of EP300 in promoting or suppressing tumors depends on tumor types." (PMID 37696842, 2023). "Comparing somatic mutation rates in SMGs between clusters using binomial regression identified PIK3CA (FDR = 0.001) and EP300 (FDR = 0.046) mutations as disproportionally more common in C1 tumours and STK11 (FDR = 0.005) and NF2 (FDR = 0.045) as enriched in C2 tumours." (PMID 36207323, 2022). "Immunostaining and quantitation of endothelial (VE-CADHERIN/CD31) and pericyte (DESMIN/aSMA) marker expression in tumor cells (GFP) showed a significant reduction in radiated, EP300-deficient tumors compared to radiated and untreated EP300-deficient or control tumors." (PMID 36261421, 2022). "EP300/CREBBP inhibitors are being trialled in EP300-, ARID1A- and CREBBP-deficient tumours." (PMID 35267442, 2022). "Recently, Wang’s team discovered that the promoter region of GPX4 binds to cyclic adenosine monophosphate response element binding protein (CREB) and that this binding can be enhanced by E1A binding protein P300 (EP300), promoting tumor proliferation, migration, invasion and angiogenesis." (PMID 36105219, 2022). "Among these, EP300 is a well-known tumor suppressor in epithelial cancer types including COADREAD." (PMID 34899838, 2021). "The histone acetyltransferase encoded by EP300 is known to initiate hypoxic responses by coupling with the HIF alpha subunit, thus enabling the induction of a range of hypoxia-responsive genes critical for tumor angiogenesis, invasion, and immune escape." (PMID 34067022, 2021). "In addition, a clonal evolution study showed an EP300 rearrangement in an EGFR-mutant tumor before transforming to SCLC through EGFR-TKI treatment." (PMID 34121659, 2021). "A higher percentage of nuclear NICD (intracellular portions of NOTCH1)-positive cells was observed in tumor samples of CREBBPmut/EP300mut patients than those of CREBBPwt/EP300wt patients, confirming the link of CREBBP/EP300 mutations with NOTCH signaling activation." (PMID 33431788, 2021). "EP300 transcriptionally activated miR-596 to serve as a tumor-repressor in EOC." (PMID 32943995, 2020). "EP300 has been found to have tumor suppressor as well as an oncogenic properties." (PMID 33167919, 2020). "Chimæra analysis suggested that the RB1 locus deletion predates the PTEN mutation and that the BRCA2 and EP300 mutations were acquired in tumor subclones that following RB1 loss, lacked the PTEN mutation." (PMID 32843649, 2020). "While the precise function of CREBBP in tumor biology remains largely unknown, several studies have reported that CREBBP and its closely related paralog EP300 behave as haploinsufficient tumor suppressors." (PMID 32493417, 2020). "Notably, glycogen content and activity of the ROS/AMPK/EP300/β-catenin axis are opposite in healthy versus tumor sections." (PMID 32603375, 2020). "Further, the inhibitory impact of EP300 on EOC cellular behaviors could be counteracted by miR-596 suppression, highlighting the tumor-repressive role of EP300/miR-596 signaling in EOC." (PMID 32943995, 2020). "Bearing in mind that the analysis was done in 19 isogenic mice, the results suggested that the ROS/AMPK/EP300/β-catenin axis might be “ON” in tumor tissue and “OFF” in adjacent healthy sections and encouraged us to study its relevance in human samples." (PMID 32603375, 2020). "At the same time, LDHA, ADM, SLC2A1 and CA9 were also decreased in EP300 knockdown ESCC cells, indicating that EP300 may promote tumor growth and progress via hypoxia in ESCC." (PMID 31632486, 2019).
tumor (continued). "The redundant targets of CREBBP and EP300 may be essential for tumor cell survival because DLBCL cell lines with truncating mutations of CREBBP are sensitive to knock-out or pharmacologic inhibition of EP300." (PMID 31788471, 2019). "In the context of cancerogenesis, CREBBP and EP300 act as tumor suppressors." (PMID 28302137, 2017). "It is unclear whether CBP/EP300 bromodomain inhibition would have tumor promoting activity in normal tissues." (PMID 26731516, 2016). "CREBBP gene and its homolog, E1A binding protein p300 (EP300) on chromosome 22, are involved in a number of basic cellular activities, such as DNA repair, growth, differentiation, apoptosis of cells, and tumor suppression by serving as transcriptional co-activators in different signaling pathways." (PMID 25599811, 2015). "In addition, SGK1 is highly expressed in tumor cells and it phosphorylates EP300 to acetylate NF-kB and is downregulated by ubiquitination via NEDD4-2." (PMID 25520040, 2014). "Around the same time, EP300 was first shown to bind to the E1A viral oncoprotein, suggesting it may also function as a tumor suppressor." (PMID 24622842, 2014). "Similarly, investigations into the role of inactivating mutations in chromatin modifiers (i.e. KDM6A, CREBBP/EP300, SMARCB1) implicate many of these genes as tumor suppressors." (PMID 24622842, 2014). "Taking all these together, our results demonstrate a strong positive association between EP300 mutations, overexpression and stemness/NK marker XCL1 related signatures, suggesting that EP300 may have a role promoting tumours to become a more aggressive subtype in ESCC." (PMID 39419971, 2024). "In line with the observations above, the other experiments testing glycolysis also showed that the EP300 deficiency is linked to a reduction in glucose uptake, LDH activity, and lactic acid production in tumor cells but increased extracellular glucose in the tumor microenvironment (TME)." (PMID 38256128, 2024). "EPHA2 and EP300 mutations consistently show decreased dNdS ratios in the presence of ATM mutation contexts compared to those without ATM mutation contexts across three tumor types, respectively." (PMID 39160568, 2024). "BRD of CREBBP/EP300 may be targeted to boost anti-tumor immune response." (PMID 36831561, 2023). "In addition, mutations in CREBBP, EP300, TP73, RBL1, RBL2 and NOTCH family genes are largely mutually exclusive, suggesting that they may play similar tumor-promoting roles in the onset of SCLC." (PMID 34168983, 2021). "Thus, CREBBP and EP300 may have distinct functions in prostate carcinogenesis, depending on tumor stage and cell model used." (PMID 33705753, 2021). "In B-lymphoma cells, the mutation or knockdown of CREBBP or EP300 inhibited H3K27 acetylation, downregulated FBXW7 expression, activated the NOTCH pathway, and downstream CCL2/CSF1 expression, resulting in tumor-associated macrophage polarization to M2 phenotype and tumor cell proliferation." (PMID 33431788, 2021). "Previous studies have shown that EP300 might act as a tumor suppressor gene or oncogene." (PMID 34616736, 2021).